XBP1 (X-box binding protein 1)
Diseases named in the same sentence as XBP1 in open-access papers (continued):
Sharing a sentence is not in itself a finding about the gene and the disease.
multiple myeloma (85 papers, 2007 to 2025). "In multiple myeloma, loss-of-function mutations in IRE1α and XBP1 play pro-oncogenic roles, suggesting that the IRE1α-XBP1 pathway acts as a tumour suppressor in some tumours." (PMID 38297380, 2024). "Consistently, myeloma patients with higher amounts of XBP1s have a poorer overall survival, and the growth of Xbp1-deficient tumor cells is impaired in xenograft models." (PMID 28860159, 2017). "Constitutive activation of UPR in mice, as demonstrated by transgenic expression of a master UPR transcription factor XBP1s (a UPR-specific splice variant of X-box binding protein 1), causes myeloma." (PMID 26108343, 2015). "Additionally, elevated expression of XBP1 in multiple myeloma patients is associated with poor survival and clinical outcome, suggesting that XBP1 is implicated in tumor progression and response to therapies." (PMID 31739582, 2019). "The exact role of XBP1 in human myeloma pathogenesis is unclear, although a recent study has shown that finding a high ratio between un-spliced and spliced variants of XBP1 in myeloma samples is linked to a poor outcome and serves as an independent prognostic factor." (PMID 24803933, 2014). "Similarly, a loss-of-function mutation in XBP1, which prevents the proper splicing of its mRNA, has been reported in rare cases of myeloma and may be associated with resistance to proteasome inhibitors." (PMID 40278350, 2025). "In addition, XBP1 mutations have been described in tumor cells from patients with multiple myeloma." (PMID 26491226, 2015). "siRNA-mediated knockdown of XBP1 also disrupts MM cell maturation, and a low level of XBP1 is a characteristic feature of the myeloma progenitor cell population." (PMID 40418254, 2025). "The UPR has been extensively characterized in various mesenchymal-derived malignancies, especially in multiple myeloma, where the IRE1α/XBP1 axis is central to plasma cell survival under proteotoxic stress." (PMID 41228282, 2025). "Myeloma patients overexpress UPR markers XBP1, BiP, ATF4, and CHOP, as well as polo-like kinase 2 (PLK2)." (PMID 40563622, 2025). "Other studies have shown that Xbp1 is more highly expressed in myelomas than in normal plasma cells." (PMID 40418254, 2025). "Taken together, these results nominate XBP1 as a particularly strong determinant of surface CD38 in myeloma plasma cells, although future investigation will be required to validate a direct or indirect relationship to CD38 transcription." (PMID 40453054, 2024). "In a prior data set of shRNA knockdown of XBP1 in myeloma plasma cells,42CD38 mRNA was decreased approximately threefold after XBP1 silencing." (PMID 40453054, 2024). "Studies have shown that XBP1 (or XBP1s) levels are positively correlated with bortezomib efficacy in patients with multiple myeloma, suggesting that XBP1s can act as a predictive marker of treatment outcomes." (PMID 38297380, 2024). "We analyzed the efficacy of targeting IRE1α-XBP1 axis and autophagy in combination with proteasome inhibitor, ixazomib in treatment of multiple myeloma." (PMID 35790913, 2022). "Recent studies showed that the IRE1α-XBP1 axis of the unfolded protein response (UPR) is up-regulated in multiple myeloma patients." (PMID 35790913, 2022). "XBP-1 is uniformly expressed in all multiple myeloma cell lines (U266 cell is a multiple myeloma cell line)." (PMID 36816476, 2022). "The effect of ERN-1 upregulation and enhanced XBP1 splicing has also been observed in proteasome inhibitor treated multiple myeloma cells, ultimately contributing to cell death in this context." (PMID 36194587, 2022). "Previous research reported that protease inhibitors can induce ERS in myeloma cells and block the IRE1α/XBP-1 pathway, inducing apoptosis of myeloma cells." (PMID 35571564, 2022). "We observed that both GNF-2 and asciminib decreased cell viability and induced XBP1 mRNA splicing in primary human myeloma cells and myeloma cell lines." (PMID 36555805, 2022).
multiple myeloma (continued). "XBP1 splicing is known to mitigate the ER stress in secretory B cells in multiple myeloma and triple-negative breast cancer cells to facilitate growth and survival." (PMID 35378132, 2022). "Unexpectedly, Sunitinib was demonstrated to effectively inhibit both IRE1 autophosphorylation and XBP1 mRNA splicing in H929 and U266 myeloma cells treated with tunicamycin (Tm) in vitro and in vivo." (PMID 33562589, 2021). "As human myeloma cells adapt to chronic ER stress and continually activate IRE1α–XBP1 signaling, we determined which endogenous UPR signaling was induced in the BM of patients with newly diagnosed multiple myeloma (NDMM) compared with the control subjects." (PMID 32878237, 2020). "To determine the effects of KIRA8 on human myeloma cells, we used IM-9 cells, which exhibit splicing of XBP1 mRNA even at the baseline (21.8% of spliced to total XBP1 mRNA ratio)." (PMID 32878237, 2020). "In this study, we investigated the role of the unfolded protein response (UPR) pathway, and in particular of the inositol-requiring enzyme-1 alpha (IRE1α)/X box-binding protein 1(XBP1) axis, in myeloma cell–induced OC differentiation." (PMID 32759820, 2020). "Resveratrol, a natural phenol found in multiple berries, has been shown to reduce the DNA-binding capacity of XBP1, thereby promoting the death of multiple myeloma cells and hepatocellular carcinoma models." (PMID 31739582, 2019). "For example, several compounds targeting either the ATP-binding pocket or the RNase domain of IRE1, and thereby reducing XBP1 mRNA cleavage, have been developed, and encouraging results in preclinical studies for multiple myeloma have been reported." (PMID 29295867, 2018). "XBP1 represents a regulator of plasma cell differentiation and overexpression of XBP1 is critical for multiple myeloma induction." (PMID 30159133, 2018). "In particular, in multiple myeloma (MM), several reports have revealed the overexpression of XBP1 and its involvement in the pathogenesis." (PMID 29581854, 2018). "For instance, XBP1 plays a key role in the endoplasmic reticulum (ER) stress response and regulates the cell survival of multiple myeloma." (PMID 28257090, 2017). "This event leads to the removal of a 26-nucleotide intron and a reading-frame shift to produce an active form of XBP1 transcription factor, which promotes the proliferation and survival of multiple myeloma cells." (PMID 28257090, 2017). "Here we further dissect the anti-myeloma mechanisms mediated by EZH2 inhibition and show that pharmacological inhibition of EZH2 reduces the expression of MM-associated oncogenes; IRF-4, XBP-1, PRDM1/BLIMP-1 and c-MYC." (PMID 28052011, 2017). "The association between UPR activity and therapeutic efficacy of proteasome inhibition was first illustrated in myeloma, in which patient serum levels of XBP1 correlated with the clinical response towards bortezomib." (PMID 27167000, 2016). "Activation of the IRE1α-XBP1 branch of the unfolded protein response (UPR) has been implicated in multiple types of human cancers, including multiple myeloma (MM)." (PMID 27634301, 2016). "It has also been identified that the blockage of IRE1α endoribonuclease activity with novel small molecules such as MKC-3946 and STF-083010, inhibits the splicing of XBP1 in multiple myeloma (MM) when in untreated condition." (PMID 26622781, 2015). "During this process, myeloma cells with preplasmoblast-like features and low levels of XBP-1, the major regulator of the unfolded protein response that at the same time determines plasmoblast differentiation and proteasome inhibitor sensitivity, accumulate." (PMID 26099967, 2015). "XBP1 overexpression in myeloma cells has also been demonstrated and it seems to be critical for multiple myeloma induction." (PMID 26491226, 2015). "Taken together, these results demonstrate that blockade of IRE1/XBP1 pathway by small-molecule compounds is a potential therapeutic for treatment of human myeloma." (PMID 23781234, 2013).
multiple myeloma (continued). "Although toyocamycin does not inhibit IRE1α phosphorylation, it prevents IRE1α-induced XBP1 mRNA cleavage and inhibits constitutive activation of XBP1 expression in myeloma cell lines as well as in samples from myeloma patients in vitro." (PMID 23781234, 2013). "In striking contrast with the other UPR markers assessed in our cells, as well as with findings reported for myeloma cells, XBP1 splicing was increased in VSMC after proteasome inhibition, particularly in concomitance with ER stress." (PMID 21297867, 2011). "Consistent to its diverse biological function, XBP1 has also been shown to be involved in many disorders including diabetes, inflammatory bowel disease, bipolar disorder, schizophrenia and multiple myeloma." (PMID 19543371, 2009). "By contrast, selective expression of spliced XBP1 protein in B-cells dramatically enhanced cell numbers, leading to a multiple myeloma-like phenotype, consistent with the ability of IRE1's RNAse function to promote cell proliferation and survival." (PMID 19137072, 2009). "MKC-3946 exerted modest cytotoxicity toward multiple myeloma cells under in vitro conditions, but significantly suppressed the growth of subcutaneous myeloma in mice by inhibiting XBP1 splicing and enhancing the apoptotic effects of the anti-cancer drugs bortezomib and 17-AAG." (PMID 40650182, 2025). "Given the important role of XBP1 splicing in myeloma plasma cells, future work will investigate the role spliced vs unspliced XBP1 in specifically regulating CD38, because this strategy may provide new avenues for CD38 manipulation." (PMID 40453054, 2024). "In addition, our gene expression analysis revealed that the genes related to IRE1α-XBP1 pathway are related to prognosis of myeloma patients." (PMID 37895838, 2023). "For instance, a higher level of spliced XBP1 in myeloma patients indicates poor prognosis." (PMID 36139473, 2022). "Furthermore, as we have previously demonstrated the effect of GNF-2 on the activation of IRE1α in β-cells, the splicing of XBP1 mRNA was induced by GNF-2 in primary myeloma cells." (PMID 36555805, 2022). "Furthermore, periplocin suppressed the constitutive activation of XBP1 and exerted cytotoxic effects in the human multiple myeloma (MM) cell lines, AMO1 and RPMI8226." (PMID 33947921, 2021). "Thus, it was suggested that Sunitinib-mediated block of XBP1 splicing is a consequence of the autophosphorylation-dependent inhibition of IRE1 RNase activity of IRE1 in myeloma cells." (PMID 33562589, 2021). "Moreover, periplocin suppressed the constitutive activation of XBP1 and exerted cytotoxic effects in the human multiple myeloma cell lines, AMO1 and RPMI8226." (PMID 33947921, 2021). "High XBP1 suggests a better prognosis in bortezomib-treated multiple myeloma." (PMID 33267910, 2020). "Overexpression of XBP1 showed a better outcome in multiple myeloma patients." (PMID 32034256, 2020). "IRE1α/XBP1 pathway is a potential therapeutic target for Myc-driven cancers and multiple myeloma." (PMID 33028359, 2020). "High expression levels of XBP1 are significantly associated with poor outcomes in human tumors, including prostate cancer, oral squamous cell carcinoma (OSCC), hepatocellular carcinoma (HCC), osteosarcoma, myeloma." (PMID 33267910, 2020). "In B-cell hematological malignancies, the IRE1-XBP1 arm is essential due to the B-cell inherent secretory phenotype and GRP78 and/or XBP1 upregulation is associated with poorer outcome in leukaemia, lymphoma and multiple myeloma." (PMID 31071975, 2019). "Inhibition of XBP1 splicing has been shown to reduce multiple myeloma cell growth." (PMID 30159133, 2018). "XBP1 splicing induced by IRE1α, prompt cellular proliferation through increased expression of cyclin A1 thus IRE1α inhibition may expose multiple myeloma cells to ER stress and reduce their survival." (PMID 30159133, 2018).
multiple myeloma (continued). "Similarly, another study indicated that XBP1s is critical in myeloma pathogenesis and a high ratio of XBP1s/XBP1 unspliced is closely correlated with poor outcome and a shortened relapse interval in patients." (PMID 26622781, 2015). "The spliced form of XBP1, XBP1s, is a transcription factor essential for myeloma cells survival." (PMID 25881299, 2015). "17-AAG treatment to myeloma cells induced splicing of XBP1, upregulation of CHOP, and activation of ATF6, and induced cell death with activation of JNK and caspase cleavage, indicating that HSP90 inhibitors induce myeloma cell death in part via ER stress and UPR pathway." (PMID 23050960, 2012). "For example, overexpression of spliced XBP1 is tightly correlated with multiple myelomas." (PMID 23110043, 2012). "Furthermore, XBP1-induced secretion of IL-6 supports the growth and survival of myeloma cells." (PMID 40179083, 2025). "Therefore, we next evaluated IRE1α-XBP1 signaling pathway, which is upregulated in myeloma cells." (PMID 37895838, 2023). "Therefore, it is of interest to evaluate whether DS/Cu could induce ICD in myeloma cells via IRE1α-XBP1 pathway." (PMID 37895838, 2023). "Interestingly, inhibition of XBP1 splicing has been shown to reduce multiple myeloma cells growth." (PMID 26491226, 2015). "IRE/XBP1 function for adequate bone resorption, signifying IRE1 as a possible target in MM and TME osteoclasts for eliminating myeloma bone disease." (PMID 40563622, 2025). "In this present study, we first show that targeting the IRE1α-XBP1 axis with small molecule inhibitors (STF-083010, A106) together with the ixazomib induces cell cycle arrest with an additive cytotoxic effect in multiple myeloma." (PMID 35790913, 2022). "As illustrated in the literature, myeloma cells resistant to Bz have reduced dependence on the UPR, reflected by the substantial decreases in XBP-1 and ATF6 expression." (PMID 34943972, 2021). "The transcription factors such as B lymphocyte induced maturation protein 1 (Blimp-1), X-box binding protein 1 (XBP-1), and interferon regulatory factor 4 (IRF4) are critical for myeloma cells differentiation and development." (PMID 34349655, 2021). "SEC61A1 is a downstream XBP1 target gene, downregulated upon inhibition of XBP1 splicing with MKC-3946 treatment in multiple myeloma cells." (PMID 32878211, 2020). "They found that SEs assist the high level transcription of genes [e.g., MYC, IRF4 (interferon regulatory factor 4), XBP1 (X-box binding protein 1), CCND2 (Cyclin D2)] that are deregulated in multiple myeloma cells." (PMID 31824865, 2019). "Elevated XBP1s expression is observed in many human tumors, including breast cancer, pancreatic adenocarcinomas, multiple myeloma, chronic lymphocytic leukemia (CLL), and plasma cell malignancy, suggesting that Xbp1 is a proto-oncogene." (PMID 28860159, 2017). "Vk*myc, XBP-1 and c-MAF transgenic mice have been shown to develop myeloma-like malignancy, with localization of disease to bone marrow plus osteolysis." (PMID 23437401, 2013). "In turn, proteasome inhibitors promote myeloma cell death and disrupt UPR signaling by preventing IRE1α-mediated splicing of the mRNA coding for active transcription factor XBP1, one of the main UPR branches." (PMID 21297867, 2011). "Inhibiting the IRE1α/XBP1 axis with Z4P enhances temozolomide efficacy in glioblastoma, while 4μ8C and STF-083010 potentiate 5-fluorouracil in colorectal cancer and show strong anti-myeloma activity." (PMID 41228282, 2025). "Moreover, we showed the possible correlation between XBP1-IRE1α signaling and ICD in myeloma cells for the first time." (PMID 37895838, 2023). "Several epitopes, such as syndecan-1 (CD138), X-box–binding protein 1 (XBP1)-unspliced, XBP1-spliced, CS1, have been identified as potential targets in multiple myeloma (MM) and smoldering multiple myeloma (SMM), and their applications against MM and SMM were also very effective." (PMID 35814435, 2022).
multiple myeloma (continued). "ChIP-seq assays showed that acetylation of H3K27 at cell cycle/mitochondrial gene promoters and super-enhancers of genes relevant for multiple myeloma biology (c-MYC, BCL-XL, CCND2, IRF4, MCL1, PIM1, PRDM1, and XBP1) was mildly increased in HDAC3 knockdown cells compared with nonsilencing cells." (PMID 36846090, 2022). "A high level of myeloma cell line dependency to MEF2C in the DepMap CRISPR/Cas9 screen, highlights an important role of this TF in the biology of MM, least because of its inferred role in activating transcription of TF such as IRF4, XBP1 and PRDM1." (PMID 34521827, 2021). "Notably, the constitutive splicing of XBP1 mRNA and expression of XBP1s protein in AMO1 myeloma cells were inhibited in a dose-dependent manner following an exposure to periplocin." (PMID 33947921, 2021). "For instance, CD138, X-box binding protein 1 (XBP1), and connecting segment 1 (CS-1) peptides are multiepitope vaccines that have elicited an influential effect on the T cell activity, resulting in the eradication of myeloma cells in vitro." (PMID 33781320, 2021). "MKC-3946, a salicylaldehydes derivative, inhibits chemically induced XBP1 splicing in multiple myeloma cell lines as well as patient-derived samples without affecting IRE1α phosphorylation in this context." (PMID 28860159, 2017). "Unfortunately, the authors concluded that this cell system was not conducive to the study of XBP1 transcription, which is critical for understanding myeloma development and progression." (PMID 23781234, 2013). "In addition to the critical roles of IRE1/XBP1 in plasma cell differentiation, a picture has emerged for the roles of UPR in myeloma." (PMID 23781234, 2013). "In myeloma cells, MG132 strongly inhibits XBP1 splicing and disrupts UPR signaling." (PMID 21297867, 2011). "All myeloma cell lines express detectable levels of total XBP1 (mean=0.6) that are significantly higher than non-myeloma cell lines (PC3, Jurkat) (mean=0.41, P<0.05), which is in agreement with published data." (PMID 19755988, 2009). "HDAC1 is highly present in CD138-negative MM cells and reduces the transcription of CHOP and Xbp1, which may induce the innate resistance of myeloma stem cells." (PMID 35681577, 2022). "Thus, HDAC inhibitors could make sensitive myeloma stem cells to MM treatment by re-establishing the production of CHOP and Xbp1." (PMID 35681577, 2022). "The IRE1/XBP1 route was described to be crucial for differentiation and survival of plasma cells, thus, we postulated that PRIMA-1 may be exerting its anti-myeloma role by inhibiting the pro-survival effects of IRE1/XBP1." (PMID 27533450, 2016).